IGF2 (insulin like growth factor 2)
Diseases named in the same sentence as IGF2 in open-access papers (continued):
Sharing a sentence is not in itself a finding about the gene and the disease.
Hypoglycemia (continued). "In some species overt insulin-like growth factor 2 (IGF-2) is thought to cause hypoglycemia." (PMID 18485198, 2008). "Consequently, systemically administered IGF2 has the potential to cause hypoglycemia." (PMID 36971212, 2023). "In a previous extensive review of this topic by de Groot and coauthors in 2007, authors noted that 41% of the IGF-2 producing tumors causing hypoglycemia were of mesenchymal origin, 43% of epithelial origin, 1% of neuroendocrine and hematopoietic origin and 14% of unknown origin." (PMID 24934576, 2014). "Our findings provide the first direct evidence that tumor vasculature is critical for manifesting clinically significant hypoglycemia, thereby complementing established molecular mechanisms such as IGF2 overexpression and impaired pro-IGF2 processing." (PMID 41858356, 2026). "We also tested binding to the IR-A of IGF2.GAA, the same fusion protein used in the reveglucosidase alpha trial and that caused transient hypoglycemia events after bolus infusions." (PMID 41023195, 2025). "This often presents as symptomatic fasting hypoglycemia, endogenous insulin and ketones suppression, and an elevated IGF-2/IGF-1 ratio." (PMID 40727482, 2025). "The mechanism of hypoglycemia for NICTH is through excess production of insulin-like growth factor 2 (IGF-2) and IGF-2 precursors secreted by underlying tumors and its insulin-like downstream effects mediated via insulin receptor activation." (PMID 41209155, 2025). "IGF-2 demonstrates insulin-mimetic properties and induces hypoglycemia through its interaction with IGF receptors and insulin receptors." (PMID 41333493, 2025). "Doege–Potter syndrome (DPS) is a rare paraneoplastic condition characterized by hypoglycemia resulting from the excessive secretion of insulin-like growth factor-2 (IGF-2) by a solitary fibrous tumor (SFT)." (PMID 41367853, 2025). "In fact, PT has been reported to be associated with other paraneoplastic syndromes, such as hypertrophic osteoarthropathy and hypoglycemia, due to IGF-2 production." (PMID 39917109, 2025). "IGF2 is highly expressed in several fibrotic animal models, such as hypoglycemia-induced right ventricular fibrosis, carbon tetrachloride-induced liver fibrosis and unilateral ureteral obstruction-induced renal fibrosis." (PMID 39744430, 2025). "When IGF-2 secretion is increased, as in NICTH, increased binding of high circulating IGF-2 to IR can induce insulin-like effects, including hypoglycemia." (PMID 41179270, 2025). "The presumed mechanism of hypoglycemia in this case involves excessive tumor synthesis of mature IGF-2 and the immature “large” pro-IGF-2, which interact with IGF and insulin receptors." (PMID 41333493, 2025). "This disease is characterized by the overproduction of IGF-2 or its high-molecular-weight precursor, "big IGF-2," which emulates insulin activity, resulting in hypoglycemia." (PMID 41333493, 2025). "With an affinity for IR-A close to that of insulin, IGF-2 can exert mitogenic effects, but can also result in clinically significant hypoglycemia, particularly when present in circulating levels 100 to 1000 times that of insulin." (PMID 40270996, 2025). "Individuals with IGF-2-mediated hypoglycemia exhibit fasting hypoglycemia marked by diminished endogenous insulin, ketones, growth hormone, and IGF-1 levels." (PMID 41333493, 2025). "Only 8 prior cases of adrenal tumors (3.4%) were previously reported with IGF-2 mediated hypoglycemia." (PMID 41209155, 2025). "Non–islet cell tumor hypoglycemia (NICTH) as a result of insulin-like growth factor-2 (IGF-2) secretion is rare, most commonly seen in tumors of mesenchymal origin, particularly fibrous tumors, and to a lesser degree, tumors of epithelial origin." (PMID 40270996, 2025).
Hypoglycemia (continued). "Conventional medical therapies for glycemic control demonstrate limited efficacy in NICTH: intravenous glucose provides only transient relief, and glucocorticoids, glucagon, GH, or somatostatin analogs often fail to suppress IGF-2-mediated hypoglycemia." (PMID 41367853, 2025). "Previous research found that corticosteroids at dosages greater than 25 mg/day of prednisolone reduced hypoglycemia episodes by 75% in medically treated individuals by decreasing "large" IGF-2." (PMID 39138498, 2024). "In this condition, changes in IGF-2 folding result in the generation of bigger peptides, which impede cellular receptors signaling pathways of counterregulatory hormones, favoring hypoglycemia states." (PMID 39138498, 2024). "Subsequent laboratory investigations demonstrated lowered IGF-1 and elevated IGF-2 levels, indicative of an IGF-2-producing tumor as the etiology of the hypoglycemia." (PMID 38666048, 2024). "In cases of IGF-2-mediated hypoglycemia, insulin, proinsulin, C-peptide, and β-hydroxybutyrate levels are typically low." (PMID 38868260, 2024). "Elevated IGF-2 levels induce hypoglycemia through heightened glucose uptake on binding to insulin receptors." (PMID 38666048, 2024). "We present two cases of IGF-2-mediated hypoglycemia: the first showing a remarkable response to tumour resection, and the second demonstrating the variable efficacy of different medical therapies in a patient with unresectable disease." (PMID 38432069, 2024). "Outcome analysis (based on mortality vs. recovery) among patients with IGF‐2‐mediated hypoglycaemia." (PMID 38411039, 2024). "Contrary to other pathologies, hypoglycemia mediated by IGF-2 often recurs despite best efforts to optimise carbohydrate and protein intake." (PMID 38432069, 2024). "Tumors associated with NICTH produce peptides, cytokines, and growth factors, including IGF-2, contributing to the development of hypoglycemia." (PMID 39219869, 2024). "This collective effect suggests that "big" IGF-2 contributes to the sustained hypoglycemia observed in (NICTH)." (PMID 39219869, 2024). "Patients with IGF-2-mediated hypoglycemia present with fasting hypoglycemia characterised by suppressed endogenous insulin, ketones, growth hormone, and IGF-1." (PMID 38432069, 2024). "When there is localised disease, surgical resection is curative with resolution of hypoglycemia and normalisation of the IGF-2/IGF-1 ratio in most cases." (PMID 38432069, 2024). "The pathophysiology of hypoglycemia in these tumors is secondary to the secretion of high molecular weight insulin-like growth factor-2 (IGF-2), also termed “big” IGF-2 in the literature." (PMID 38911593, 2024). "Here, in relation to NICTH, we also revealed the simultaneous overexpression of IGF2 mRNA, miR-483-5p, and miR-483-3p in SFT tissues causing hypoglycemia." (PMID 39689018, 2024). "Pro-IGF-2 is thought to induce hypoglycemia by increasing the bioavailability of IGF-2 through altered binding with insulin-like growth factor–binding proteins and other associated proteins." (PMID 39372824, 2024). "Insulin‐like growth factor‐2 (IGF‐2)‐mediated hypoglycemia is a rare yet clinically significant entity with considerable morbidity and mortality." (PMID 38411039, 2024). "A growing body of evidence supports screening for IGF‐2 in non‐diabetic persons with hypoglycaemia and suppressed insulin and c‐peptide levels." (PMID 38411039, 2024). "In approximately half of the patients with IGF‐2‐mediated hypoglycaemia, the tumour is identified before developing hypoglycaemia." (PMID 38411039, 2024). "In our study, we found a lower IGF‐2:IGF‐1 ratio in patients presenting with hypoglycaemia as the first manifestation of NICTH." (PMID 38411039, 2024). "Our analysis of the IGF‐2 to IGF‐1 ratio disclosed lower ratios in patients for whom hypoglycaemia constituted the initial clinical presentation." (PMID 38411039, 2024).
Hypoglycemia (continued). "Here, we present a case of benign intra-abdominal leiomyoma that presented with refractory hypoglycemia, which we suspect was due to tumor secretion of IGF-2 leading to NICTH." (PMID 38911593, 2024). "An IGF-2/IGF-1 ratio above 10 is highly suggestive of IGF-2-mediated hypoglycemia if the IGF-2 level is normal or elevated." (PMID 38432069, 2024). "Glucocorticoids mitigate hypoglycemia by suppressing pro-IGF-2 production, increasing hepatic gluconeogenesis, promoting lipolysis, and reducing peripheral glucose uptake." (PMID 38432069, 2024). "As with other described NICTH tumors, the pathogenesis of hypoglycemia in Doege–Potter syndrome is thought to be secondary to tumor secretion of “big” IGF-2." (PMID 38911593, 2024). "The diagnosis of IGF‐2‐mediated mechanism behind NICTH is sometimes complex and needs careful evaluation and ruling out other more common causes of hypoglycaemia." (PMID 38411039, 2024). "IGF-2 exerts insulin-like activity and promotes hypoglycemia by binding to IGF receptors and insulin receptors." (PMID 38432069, 2024). "It was reported that IGF2, similar to insulin, can promote hypoglycemia by enhancing glucose uptake by skeletal muscle and inhibiting glucose release from the liver." (PMID 37152930, 2023). "Although many SFTs exhibit overproduction of IGF2, in only less than 5% of cases can a symptomatic hypoglycemia be observed." (PMID 37469410, 2023). "The differential diagnosis of hypoglycemia should include rare causes such as DPS, and the IGF-2/IGF-1 ratio is a useful tool." (PMID 37373678, 2023). "Ultimately, increasing levels of pro- and big-IGF2 suppress PCSK4 expression, and all together lead to a vicious cycle of high IGF2 and pro-IGF2 levels, triggering severe hypoglycemia." (PMID 37598269, 2023). "IGF2, similar to insulin, can promote hypoglycemia by enhancing glucose uptake by skeletal muscle and inhibiting glucose release from the liver." (PMID 37152930, 2023). "IGF2‐induced hypoglycemia is seen in several cancers (e.g. Wilms's tumor, non‐islet cell tumor hypoglycemia) due to hyper‐secretion of IGF2 by the tumor itself." (PMID 36971212, 2023). "In the male, levels of insulin and C‐peptide were suppressed and a diagnosis of paraneoplastic hypoglycemia by IGF‐2 secretion was made with increased glucose disposal in skeletal muscle proven by 18F‐FDG-PET-CT." (PMID 36703082, 2023). "Results showed a serum IGF-2 of 78.2 nmol/L, IGF-1 of 3.5 nmol/L (4.4–21.8) and an IGF-2:IGF-1 ratio of 22.3 which is consistent with IGF-2 mediated hypoglycemia." (PMID 36303203, 2022). "Insulin-like growth factor 2 (IGF-2) mediated hypoglycemia is exceedingly rare in clinical practice." (PMID 36303203, 2022). "Typically, IGF-2 mediated hypoglycemia is observed in the setting of mesenchymal and epithelial neoplasia." (PMID 36303203, 2022). "For example, in human serum the concentration of IGF-2 is higher than that of insulin and, considering the fact that IGF-2 is able to activate insulin receptors, this would lead to hypoglycemia if IGF-2 was present in its unbound form." (PMID 33673334, 2021). "SRS and IGF2 hypomethylation should be considered early in the differential diagnosis of recurrent ketotic hypoglycemia in childhood, as patients benefit from early GH treatment." (PMID 33922271, 2021). "Patients with IGF2-producing tumors have impaired glycogenolysis and gluconeogenesis with hypoglycemia and suppressed insulin secretion." (PMID 33849624, 2021). "We report on a patient with IGF2 hypomethylation who presented with severe recurrent hypoglycemia at the age of 19 months." (PMID 33922271, 2021). "In non-islet cell tumor hypoglycemia (NICTH), a considerable high molecular weight form of insulin like growth factor 2 (IGF-2) is formed, which abnormally binds to insulin receptors in the tissues and causes hypoglycemia." (PMID 33841338, 2021).
Hypoglycemia (continued). "Our case demonstrates that SRS and isolated IGF2 hypomethylation should be considered early in the diagnosis of recurrent hypoglycemia in childhood, especially in combination with small gestational age and poor growth." (PMID 33922271, 2021). "Although solitary fibrous tumor (SFT) is a rare mesenchymal neoplasm, it has been estimated that 4–6% of SFT patients develop hypoglycemia due to circulating big IGF-2." (PMID 32993631, 2020). "We encountered a case with SFT, who, 17 years after detection of the SFT, experienced both recurring episodes of hypoglycemia and the development/growth of another novel tumor, with high circulating big IGF-2 levels." (PMID 32993631, 2020). "An 84-year-old man had a recurrent left pleural solitary fibrous tumor releasing high molecular weight insulin-like growth factor 2 and experienced a frequent syncope accompanied by hypoglycemia." (PMID 32025979, 2019). "In NICTH, there are mainly three mechanisms leading to hypoglycemia: tumor cells secrete excessive high-molecular-weight IGF-2 precursor, IGF-1, and insulin." (PMID 29166433, 2019). "Ectopic insulin-like growth factor (IGF)-2 production is a rare complication of an array of epithelial and mesenchymal tumors, and can clinically manifest as life-threatening hypoglycemia." (PMID 29340167, 2018). "Due to cross-reactivity at the insulin receptor, ectopic IGF-2 can precipitate a clinical syndrome that mimics the fasting hypoglycemia characteristic of patients with insulinoma." (PMID 29340167, 2018). "Here, we describe a case of ectopic IGF-2 production from a malignant hemangiopericytoma and discuss the management of resultant hypoglycemia." (PMID 29340167, 2018). "Following this definitive therapy, hypoglycemia resolved and IGF-2 level, measured two weeks after final radiation treatment, declined to 380 ng/mL." (PMID 29340167, 2018). "Studies have shown that tumors produce IGF2, which increases the consumption of peripheral glucose and decreases the glucose production in the liver, resulting in hypoglycemia." (PMID 29694637, 2018). "The paraneoplastic syndrome of hypoglycemia due to IGF2 hyper-secretion by pleural SFT is more commonly known as “Doege-Potter syndrome”." (PMID 30168002, 2018). "The paraneoplastic syndrome of hypoglycemia that occurs particularly due to insulin-like growth factor 2 (IGF-II), which is secreted from fibrous tumor cells, is called Doege-Potter syndrome." (PMID 28784156, 2017). "Increased glucose uptake, lower insulin and glucagon secretion, decreased lipolysis and liver gluconeogenesis are some effects of the massive secretion of IGF2 that lead to hypoglycemia." (PMID 27134683, 2016). "It is due to the structural and biochemical homology between IGF-2 and insulin that an unregulated and elevated level of IGF-2 stimulates glucose metabolism pathways thus leading to hypoglycemia." (PMID 24934576, 2014). "Diagnosis of paraneoplastic IGF-2 induced hypoglycemia is an important and time sensitive consideration since earlier detection of tumors provides a better opportunity for complete resection and subsequent resolution of hypoglycemia." (PMID 24934576, 2014). "Prepro IGF-2 molecules (known as “big IGF-2”) have also been shown to have biologic activity and can produce hypoglycemia in the setting of a normal IGF-2 level." (PMID 24934576, 2014). "Due to the structural and biochemical homology between IGF-2 and insulin, elevated levels of IGF-2 can result in hypoglycemia." (PMID 24934576, 2014). "Tumors producing elevated levels of circulating IGF-2 with resulting hypoglycemia are categorized as NICTH." (PMID 24934576, 2014). "It ameliorates hypoglycemia by increasing gluconeogenesis and by suppressing the production of ‘big’ IGF2." (PMID 24616774, 2013). "Non Islet cells tumor hypoglycemia (NICTH) is due to an oversecretion of incompletely processed precursors of IGF-2 ('big'-IGF-2) by the tumor." (PMID 21967988, 2011).
Hypoglycemia (continued). "One case report investigated the level of IGF-2 in a horse with renal cell carcinoma and hypoglycemia, but the data were inconclusive." (PMID 18485198, 2008). "By binding the IR-A, IGF-2 can induce clinically significant hypoglycemia." (PMID 40270996, 2025). "IGF-2 affinity for the insulin receptor (IR) can result in clinically significant hypoglycemia." (PMID 40270996, 2025). "Although insulinoma is typically the primary suspicion, diminished insulin and C-peptide levels during hypoglycemia necessitate investigation for other etiologies, including insulin-like growth factor 2 (IGF-2)-secreting neoplasms like gastrointestinal stromal tumors (GISTs)." (PMID 41333493, 2025). "IGF‐2 stimulates insulin receptors and increases glucose utilization, leading to hypoglycemia." (PMID 40550558, 2025). "However, in NICTH, IGF-2 is grossly overexpressed by tumor cells, especially of mesenchymal and epithelial origin, exerting an insulin-like effect on the body, promoting hypoglycemia by binding both IGF receptors and insulin receptors." (PMID 40727482, 2025). "Importantly, unlike insulinomas, these episodes typically do not coincide with elevated insulin levels but rather result from increased secretion of IGF‐2, leading to hypoglycemia." (PMID 40550558, 2025). "SFTs are part of a group of tumours causing hypoglycaemia via the secretion of IGF-2 (non-islet cell tumour-induced hypoglycaemia (NICTH))." (PMID 39931615, 2025). "IGF-2 exerts insulin-like bioactivity that directly induces hypoglycemia, while simultaneously suppressing endogenous insulin and C-peptide secretion—exactly matching the patient’s biochemical profile (low C-peptide and hypoglycemia)." (PMID 41585808, 2025). "In addition to tumorigenesis, IGF-2 and its precursor molecules have the potential to induce hypoglycemia leading to NICTH." (PMID 39372824, 2024). "As well, nature may have developed a mechanism to reduce the possibility of IGF2-induced hypoglycemia by modulating the binding affinity of IGF2 to IR and by expressing IGF-binding proteins." (PMID 38521788, 2024). "In the context of IGF‐2‐mediated hypoglycaemia, the hypothalamic–pituitary axis might respond to the elevated levels of IGF‐2 (and its resultant effects on blood glucose levels) by adjusting the secretion of other hormones." (PMID 38411039, 2024). "Hypoglycaemia, which may be the sole symptom at disease onset, is mediated by the secretion of high-molecular-weight insulin-like growth factor (IGF-2)." (PMID 39138498, 2024). "As a result, "big" IGF-2 circulates in its free form, leading to several biochemical and physiological effects that contribute to hypoglycemia, such as impaired glucose release from the liver, increased glucose utilization, and suppression of counter-regulatory hormones." (PMID 39219869, 2024). "Non-islet cell tumor hypoglycemia (NICTH) is a rare paraneoplastic syndrome characterized by insulin-like growth factor-2 (IGF-2) release, often associated with diverse tumor types." (PMID 39219869, 2024). "The most common mechanism of hypoglycemia is the production of high molecular weight IGF-2." (PMID 38911593, 2024). "A case report showed that patients with tumors that overproduced IGF2 developed hypoglycemia." (PMID 37152930, 2023). "However, a small subset of patients developed transient hypoglycemia shortly after the drug administration, which was attributed to a pharmacologic effect of the IGF2 moiety." (PMID 37463048, 2023). "Thus, this increased tissue-bioavailability of IGF2 prohormones can lead to hypoglycemia, known for example, for the NICTH17,18,26." (PMID 37598269, 2023). "The induced hypoglycemia in EAC-untreated mice may be a result of glucose utilization by tumor cells that overproduce partially processed insulin-like growth factor-2 (IGF-2), which stimulates insulin receptors." (PMID 38098043, 2023).